VIM (vimentin)
Diseases named in the same sentence as VIM in open-access papers (continued):
Sharing a sentence is not in itself a finding about the gene and the disease.
colon adenocarcinoma (8 papers, 2006 to 2024). "A recent biological study reported that the decreased expression of E-cadherin and increased expression of N-cadherin and vimentin in tumor cells of PMP were more significant than in those of adenocarcinoma of the colon." (PMID 22844275, 2012). "A panel of immunohistochemical stains, including CK 7, CK 20, vimentin, and estrogen receptors, may be used in order to differentiate the colonic adenocarcinoma from the müllerian endometriotic adenocarcinoma." (PMID 17164003, 2006). "Further IHC and Western blot analysis showed that Vimentin and DCLK1 were highly expressed in colonic adenocarcinoma of Villin-CXCR7 mice, which was abrogated by Verteporfin." (PMID 36210463, 2022). "In a colon adenocarcinoma study, ATP6V1C2 knock-down (KD) affected WNT pathway-related genes and epithelial-to-mesenchymal transition (EMT)-related genes, with a decrease in fibronectin-1, vimentin and increase in E-Cadherin, thus attenuating metastasis." (PMID 39696035, 2024). "Although not formally proven, procollagen 11A1+ colon adenocarcinoma stromal cells, being spindle-shaped, seem to simultaneously express alpha smooth muscle actin and vimentin, but no desmin; these traits confer to them a myofibroblast-like phenotype rather than a pericyte one." (PMID 25417197, 2014).
colorectal adenocarcinoma (8 papers, 2006 to 2024). The most common type of colorectal carcinoma. "Immunohistochemistry confirmed a broad expression of vimentin in several types and stages of cancer, such as colorectal adenocarcinoma." (PMID 35681575, 2022). "Like colorectal adenocarcinoma, this process is characterised by increased N-cadherin and decreased E-cadherin expression, although this may be more exaggerated in PMP and is also associated with increased vimentin expression." (PMID 17031402, 2006). "We further confirmed the correlation by costaining FFPE colorectal adenocarcinoma samples with antibodies against α5 (green) and two CAF markers: α‐SMA (red) and vimentin (red)." (PMID 31600854, 2019).
epithelioid sarcoma (8 papers, 2011 to 2024). An aggressive malignant neoplasm of uncertain differentiation, characterized by the presence of epithelioid cells forming nodular patterns. "Epithelioid sarcoma is characterized by strong and diffuse vimentin positivity, epithelioid and spindle tumor cells, and cells arranged in cell nodules with a pseudogranulomatous appearance; therefore, it can also be excluded." (PMID 38542211, 2024). "Diffuse sheet-like epithelioid growth pattern with extensive distribution of necrosis and positive staining for vimentin suggested epithelioid sarcoma." (PMID 26208724, 2015). "In the two epithelioid sarcoma cell lines, E-CADHERIN was strongly induced by panobinostat in a dose-dependent manner and conversely, VIMENTIN expression was reduced." (PMID 34281526, 2021). "Both forms of epithelioid sarcoma typically coexpress CAM5.2, AE1/AE3, EMA, CK19, vimentin and are CD34 positive in 50 to 70% of cases." (PMID 31915021, 2020). "Epithelioid sarcoma shows a strong and diffuse positivity to EMA and vimentin." (PMID 33866513, 2021). "Epithelioid sarcoma showing strong and diffuse positivity to EMA and Vimentin was also excluded." (PMID 33866513, 2021). "Both tumours show morphological and immunohistochemical overlap with coexpression of epithelial markers and vimentin; however epithelioid sarcomas express CD34, a marker which is typically absent in MRT." (PMID 25243090, 2014).
idiopathic pulmonary fibrosis (8 papers, 2014 to 2025). Idiopathic pulmonary fibrosis (IPF) is a nonneoplastic pulmonary disease that is characterized by the formation of scar tissue within the lungs in the absence of any known cause. "Many EMT inducers act directly or indirectly by repressing E-cadherin, increasing vimentin and α–smooth muscle actin (αSMA), a set of incidences that promote accumulation of myofibroblasts in injured tissues, which characterizes fibrotic diseases, including idiopathic pulmonary fibrosis (IPF)." (PMID 31591327, 2019).
invasive carcinoma (8 papers, 2006 to 2023). A carcinoma that is not confined to the epithelium, and has spread to the surrounding stroma. "The expressions of N-cadherin, Snail, Twist, Vimentin and Zeb1, and number of cells that demonstrated loss of E-cadherin were significantly higher in invasive carcinomas in contrast to normal tissue and DCIS samples (p < 0.05)." (PMID 31889895, 2019). "In line with all these studies, our results also demonstrated that there was a significantly higher rate of E-cadherin loss and higher expressions of N-cadherin, Snail, Twist, Vimentin and Zeb1 in invasive carcinoma in comparison to DCIS." (PMID 31889895, 2019). "Interestingly, loss of E-cadherin and gain of cytoplasmic β-catenin and vimentin were observed in invasive carcinoma compared with adjacent in-situ carcinoma and normal epithelium." (PMID 31885577, 2019). "N-cadherin, Snail, Twist, Vimentin, and Zeb1 were expressed in 19.8% (23/116), 19% (22/116), 9.5% (11/116), 16.4% (19/116),and 12.9% (15/116) of the invasive carcinomas." (PMID 31889895, 2019). "The current investigation explores the expression of EMT markers (N-cadherin, Snail, Twist, Vimentin, Zeb1, E-cadherin) in invasive carcinomas and DCIS." (PMID 31889895, 2019). "For three of them (cadherin 11, annexin A1, and vimentin), we observe the same expression pattern as published by Nagaraja and colleagues for the transition from in situ to invasive carcinoma." (PMID 17069663, 2006). "Previous studies confirmed that overexpression of SPHK1 was associated with decreased expression of E-cadherin and increased expression of vimentin, suggesting that SPHK1 plays a pivotal role in the EMT of invasive carcinoma cells." (PMID 35126792, 2022). "This conclusion was based on the detection of vimentin in all invasive carcinomas and lymph node metastases, but not in cervical intraepithelial neoplasia 3 (CIN3) lesions." (PMID 37717112, 2023). "The primary lesion lacked vimentin expression and the cell line was shown to be cytokeratin positive which is consistent with basal type invasive carcinoma." (PMID 18179684, 2008). "Nonetheless, the role of vimentin in EMT needs further clarification, and it is not clear how VIM expression is fine-tuned from its absence in normal cells to its (over)expression in invasive carcinoma cells." (PMID 36594099, 2023).
metastatic melanoma (8 papers, 2008 to 2022). A melanoma that has spread from its primary site to another anatomic site. "In the pursuit of finding biomarkers that predict treatment response, we evaluated the association between serum biomarkers of collagen and vimentin turnover and outcomes in metastatic melanoma patients treated with the anti-CTLA-4 antibody ipilimumab (IPI)." (PMID 30567561, 2018). "Overexpression of vimentin has been demonstrated in metastatic melanoma, and correlates with a poor prognosis." (PMID 36230844, 2022). "Vimentin was expressed in all biopsies derived from both nodular and metastatic melanoma; however, the level of expression was elevated in nodular melanoma, which is the initial stage of the disease." (PMID 23785295, 2013). "Melanocytes contain vimentin, an intermediate filament usually expressed in primary and metastatic melanoma cells." (PMID 18445301, 2008). "Immunohistochemical study (positive for S100, HMB45, and vimentin and negative for CK, CD10, CK20, CK7, CD30, LCA, EMA, and chromogranin) confirmed metastatic malignant melanoma." (PMID 24795827, 2014).
papillary thyroid carcinoma (8 papers, 2018 to 2026). "For instance, miR-31 presents low expression levels in papillary thyroid cancer, while its overexpression promotes vimentin, N-cadherin, p-AKT and p-ERK downregulation, as well as decreased cell migration and invasion." (PMID 34680488, 2021). "In our previous work, we demonstrated that ouabain decreased cell migration and the expression of epithelial to mesenchymal transition (EMT) markers associated with tumor cell aggressiveness, such as vimentin, SNAIL-1 and MMP-9, in the human thyroid papillary cancer TPC-1 and BCPAP cell lines." (PMID 36551653, 2022). "Similarly, the overexpression of miR-520a-3p also upregulated E-cadherin, and decreased the expression of N-cadherin and vimentin, while inhibiting cell migration and invasion in papillary thyroid cancer." (PMID 34680488, 2021). "MiR-144-3p also proved to be an EMT inducer in papillary thyroid cancer, as it was responsible for decreased E-cadherin and thyroid-specific transcription factor PAX8 expression while upregulating vimentin and N-cadherin." (PMID 34680488, 2021). "Moreover, in papillary thyroid cancer, high miR-221 expression was associated with EMT activation once it was related to the occurrence of lymph node metastasis, as well as enhanced cell invasion and migration along with high levels of vimentin, N-cadherin and SNAIL." (PMID 34680488, 2021). "On the contrary, the papillary thyroid carcinoma stained positive for CK, CK19, and thyroglobulin, and negative for vimentin." (PMID 41124647, 2026).
silicosis (8 papers, 2016 to 2025). Silicosis is a respiratory disease caused by breathing in (inhaling) silica dust. "In the region of severe fibrosis, namely, silicon nodules, the vimentin-positive cells in the silicosis model group were more common than that in the ordinary saline control group, and the positive expression of E-cadherin decreased significantly." (PMID 39258668, 2024). "In rat and mouse silicosis models, the expression of E-cad decreased significantly, while the expression of Vimentin and α-SMA increased significantly." (PMID 35886594, 2022). "In contrary, NAC administration notably elevated E-cadherin expression but decreased vimentin and Cytochrome C expressions in CS-induced mice silicosis model." (PMID 31273057, 2019). "In line with expectations, we found a significant decrease of E-cadherin and increase of vimentin as well as Cytochrome C in mice silicosis model." (PMID 31273057, 2019). "As evidence, the vimentin expression was also significantly increased in the silicosis model group." (PMID 36430681, 2022). "Moreover, the increased abundances of Wnt3a, NOX4, α-SMA, and vimentin were further corroborated to be predominantly expressed in the silicosis nodules of silica-challenged lungs as determined by the immunofluorescent staining (IF) assay." (PMID 33376577, 2020). "The results revealed a reduction in the epithelial marker E-Cad, while the expression levels of the mesenchymal markers α-SMA, Vimentin, and ZEB1 were notably elevated in the lung tissue of silicosis mice." (PMID 40423444, 2025). "Immunohistochemical, Western blot, and PCR results showed that glycyrrhizic acid promoted the expression of EMT marker E-cad and inhibited the expression of N-cad, Vimentin, and α-SMA, suggesting that glycyrrhizic acid can inhibit the EMT process in silicosis." (PMID 35886594, 2022). "Many vimentin (laser confocal cell marker for myoblasts)- and FSP-1 (fibroblast marker)-positive cells were observed in silicon nodules, confirming the differentiation of bronchoalveolar epithelial cells into myoblasts during silicosis." (PMID 39258668, 2024). "However, in silicosis rats treated with metformin, the expression level of E-Cad but α-SMA and Vimentin were significantly recovered in a dose-response relation with the concentration of metformin compared with the silica group (p < 0.05)." (PMID 34434111, 2021). "In silicosis nodules, there was sporadic or weak expression of SP-A or α-Ac-Tub, and there was strong expression of vimentin, which was not accompanied by the co-expression of α-Ac-Tub." (PMID 27577858, 2016).
adrenal carcinoma (7 papers, 2007 to 2023). A carcinoma involving a adrenal gland. "For these experiments, SW13/cl.2 adrenal carcinoma cells stably transfected with a green fluorescent protein (GFP)-fusion constructed of the intermediate filament protein vimentin (GFP-vimentin wt) were used." (PMID 32369981, 2020). "In HE staining, the morphology of two tumors were slightly different; therefore, we evaluated two HCC markers (GPC3 and AFP) and two adrenal carcinoma markers (vimentin and Melan-A) via IHC staining." (PMID 31696344, 2019). "SW13 cells are an adrenal carcinoma cell line that lacks type III IFs such as vimentin and desmin, allowing one to evaluate newly synthesized IF formation." (PMID 31371504, 2019). "In terms of adrenal carcinoma markers vimentin and Melan-A, vimentin was negative in the HCC and adrenal tumor, and Melan-A was negative in the HCC." (PMID 31696344, 2019). "In adrenal carcinoma, GPC3 is not expressed, and the positivity rates of vimentin and Melan-A were 54% and 84%, respectively." (PMID 31696344, 2019).
ductal carcinoma (7 papers, 2006 to 2020). "Therefore, vimentin expression appears to predict survival in ductal breast carcinoma." (PMID 24527079, 2014).
endometrioid carcinomas (7 papers, 2006 to 2025). "On the malignant spectrum, the ductal variant of the tumor should be differentiated from endometrioid adenocarcinoma, which is usually positive for ER, PR, and vimentin." (PMID 31266530, 2019). "Comparison between diploid and aneuploid endometrioid carcinomas identified 20 proteins, with VIM, GRB2, and ACTB highlighted as the most important network nodes." (PMID 39194522, 2024). "Comparison between normal endometrium and diploid endometrioid carcinomas identified 19 proteins and interaction networks, with VIM, ACTB, and NFκB being the most relevant proteins." (PMID 39194522, 2024). "In this scenario, the panel of Progesterone receptor (PR) & vimentin (both positive in endometrioid carcinoma) with p16, Carcinoembryonic antigen (positive in endocervical carcinoma) is very helpful." (PMID 36200017, 2022). "Morphologic and immunohistochemical features were typical of an endometrioid adenocarcinoma (cytokeratin (CK) 7-positive, vimentin-positive, CK20-negative)." (PMID 17164003, 2006). "Eight common proteins were identified between normal endometrium with diploid endometrioid carcinomas and diploid with aneuploid endometrioid carcinomas, namely ACTB, ATP5B, ATP5E, INS, IVNS1ABP, LMNB, PLS1, and VIM." (PMID 39194522, 2024). "Similar to serous and endometrioid carcinomas, CCCs express CK7, B72.3 and BerEP4 while CA125 and vimentin are positive in approximately 50% of the cases." (PMID 32215023, 2020).
inflammatory bowel disease (7 papers, 2018 to 2025). A spectrum of small and large bowel inflammatory diseases of unknown etiology. "Crohn’s disease is a genetic inflammatory bowel disease within the gastrointestinal tract, and is associated with upregulation of vimentin protein levels." (PMID 30248895, 2018). "Similarly, fucosyltransferase 2 (FUT2) and serum vimentin (VIM) have been implicated in other chronic inflammatory conditions, such as inflammatory bowel disease, but their roles in AD remain uncharacterized." (PMID 41583462, 2025). "Indeed, inflammatory bowel disease (IBD) increases the risk of colorectal cancer when methyl groups are covalently bound to cytosines in the CpG islands in stool DNA, specifically in loci containing BMP3, VIM, EYA4 and DRG4 genes." (PMID 38299096, 2023). "Previous work from our group demonstrated that vimentin interacts with the pattern recognition receptor (PRR) nucleotide-binding oligomerisation domain-containing protein 2 (NOD2), a bacterial sensor protein that is strongly associated with inflammatory bowel disease Crohn’s disease (CD)." (PMID 30699149, 2019).
Insulin resistance (7 papers, 2012 to 2024). Increased resistance towards insulin, that is, diminished effectiveness of insulin in reducing blood glucose levels. "We found specific rearrangements of the actin cytoskeleton and slit diaphragm proteins (Nephrin, P-Cadherin, Vimentin) associated with this insulin resistance in palmitic-treated podocytes." (PMID 26545114, 2015). "The elevated expression of vimentin in camel hump adipocytes could contribute to peripheral insulin resistance." (PMID 35903143, 2022). "We have found a reduction of vimentin, a mesenchymal marker in visceral fat depot, which could exacerbate inflammation and partial insulin resistance observed after chronic leptin treatment." (PMID 23056516, 2012). "In mice, a lack of vimentin avoids obesity and insulin resistance." (PMID 35903143, 2022).
invasive ductal carcinoma (7 papers, 2011 to 2025). "Rigorous immunohistochemical analysis was employed to assess the expression of vimentin, beta-catenin, and E-cadherin in primary tumors, tumor buds, and lymph node metastases (LNMs) from 137 cases with an invasive ductal carcinoma triple-negative phenotype diagnosed between 2018 and 2024." (PMID 39371729, 2024). "Our triple-negative tumors have many of the characteristics of basal tumors: invasive ductal carcinoma, grade 3 tumors, CK5+, Vimentin+, highly proliferative markers (increased Ki-67+ and Cyclin A2+)." (PMID 37273492, 2023). "In addition, the spindle cell lesion reveals strong expression for vimentin and negative immunoreactivity for Pan-CK, CK5/6, HM-CK, and the tumor cells in the axillary LNs and skin lesions were compatible with those of invasive ductal carcinoma." (PMID 24400686, 2014).